IL10 (interleukin 10)
Diseases named in the same sentence as IL10 in open-access papers (continued):
Sharing a sentence is not in itself a finding about the gene and the disease.
tumor (continued). "IL-10-producing macrophages are reported to be M2 polarized cells that, in the context of tumours, can facilitate tumour progression, confirming the hypothesis about the role of soot particle-induced IL-1-like cytokines in the tumour microenvironment." (PMID 28223692, 2017). "Tumor infiltrating lymphocytes in NPC secret IL-10, which can block CTL responses." (PMID 28056887, 2017). "The role of IL-10 in tumor pathogenesis and development is a double-edged sword." (PMID 29029504, 2017). "The overall pattern of released cytokines in the present study was similar; however, the anti-inflammatory cytokine IL-10 was also detectable in cycles 2 and 3, possibly because of the larger tumor load in patients with relapsed/refractory ALL, compared with MRD-positive ALL." (PMID 28533941, 2017). "A recombinant thymidine kinase (TK)-deleted Lister strain vaccinia OV armed with murine IL-10 was able to elicit tumour rejection in two murine pancreatic ductal adenocarcinoma (PDAC) models by prolonging the oncolytic potential of the OV and modulating innate and adaptive immune responses." (PMID 29157300, 2017). "Further evidence suggests the decrease in the concentration of different tumor-derived molecules (e.g., TGFβ, IL-10) because of tumor removal may be involved in the decrease of MDSCs in association with the downregulation in its signature suppressor molecules." (PMID 28414726, 2017). "Interestingly, this patient also exhibited an increase over pre-existing baseline tumor-specific IL-5 and IL-10 cytokine responses." (PMID 29258618, 2017). "The effect of R2016 on secretion of TGF-β1, IL-10, and IL-12 from the tumor cells was investigated." (PMID 28282460, 2017). "STING ablation enhanced CD8+ T cell infiltration, tumor cell killing, decreased suppressor cell infiltration and IL-10 production in tumor microenvironment in LLC mice model, indicating the role STING signaling in attenuation of CD8+ T cell functions during tumorigenesis." (PMID 29156566, 2017). "In this regard, IL-10 stimulates cytotoxicity of CD8+ T cells promoting tumor rejection." (PMID 28333114, 2017). "Evidence suggests that IL-10 facilitates the shift of T cell’s cytokine production pattern from a T helper 1 (Th1) immune-phenotype (with anti-tumor activity) to Th2 immuno-phenotype (with pro-tumor activity)." (PMID 28346397, 2017). "IL-10 is an immunosuppressive cytokine and plays a role as a mediator of tumor regression." (PMID 29312337, 2017). "These factors contribute in a cumulative way to the creation of the proinflammatory and immunosuppressor microenvironment that favors tumor proliferation The IL-6 and the IL-10 have received major attention owing to their correlation to poor prognosis and inadequate response to treatment." (PMID 28848618, 2017). "However, co-treatment with both DFMO and Trimer PTI significantly increased the levels of IL-10, IFN-γ, and MCP-1, i.e., cytokines associated with increased immune activity in the tumor and tumor microenvironment." (PMID 29137411, 2017). "Tumor endothelial cells are also able to secrete inhibitory molecules such as IL-6 or IL-10." (PMID 28665313, 2017). "Neutralization of IL-10 and VEGF-A reduced tumour proli feration caused by GAS5 knockdown." (PMID 28099146, 2017). "However, increased IL‐10 production was significantly observed in CT26 tumour‐derived MDSCs activated by BaF3‐RAE1ε in vitro, and arginase activity remained unchanged." (PMID 28276625, 2017). "Interestingly, the macrophage subsets M(IFN-γ + LPS) and M(IL-10 + TGFβ) that demonstrated highest tumor cell phagocytosis in the presence of TTI-621 were found to expressed highest level of CD64, and CD32/CD16, respectively." (PMID 29084248, 2017). "IL-10 is detected in a variety of freshly excised human tumour samples." (PMID 28810829, 2017).
tumor (continued). "For instance, the chemokine CCL2 and macrophage colony-stimulating factor were shown to recruit inflammatory monocytes to the tumour site, and then differentiate into TAMs in response to IL-4, IL-10, IL-13 and other cytokines in the tumour microenvironment and promote tumour metastasis." (PMID 29065107, 2017). "The IL-10 mRNA levels in the tumors of tumor-bearing mice were measured by RT-PCR." (PMID 28460478, 2017). "Thus, although cultures of NK cells from patients with different tumor types exhibited differences in individual cytokines such as IL-10, they all exhibited lower cytotoxicity and less IFN-γ secretion." (PMID 28424683, 2017). "Furthermore, pDCs induce IL-10 production in T cells, leading to a crosstalk with mDCs and suppression of their function to prime a tumor antigen T cell response." (PMID 28536351, 2017). "Moreover, acquisition of an M2-like phenotype is also caused by secretion of tumour-derived cytokines such as IL4, IL10, and IL13." (PMID 29065107, 2017). "Interestingly, vaccination combined with simultaneous blockade of IL-10 and PD-L1 induced stronger immune responses, resulting in a higher therapeutic efficacy in tumor-bearing mice." (PMID 27926522, 2017). "A wealth of evidence now exists to suggest that IL-10 functions as both an immune-suppressive and immune-stimulating or anti-tumor cytokine, depending on the context of its expression, thus the role of IL-12-induced IL-10 in this setting requires further study." (PMID 29123084, 2017). "When infiltrated, macrophages increase the expression of mannose and galactose receptors as well as the production of VEGF, cyclooxygenase-2 (COX-2)-derived prostaglandin E2 (PGE2), and IL-10, thus rendering the microenvironment against inflammation and favorable to tumor development." (PMID 28970834, 2017). "High post-NAC tumour levels of FOXP3+ T cells, IL-10, and IL-17 were associated with a failed pCR." (PMID 27777963, 2016). "Interestingly, despite the increase in PD-L1 expression observed in tumour lysate-loaded DCs, IL-10 production was marginal in antigen loaded DCs also when supernatants were analysed by ELISA." (PMID 26795765, 2016). "As dectin-1 was found predominantly on RCC cells in our study, tumor cell might also be activated through this signal and facilitate specific immune regulatory cytokine production such as IL-10 and IL-23." (PMID 27600310, 2016). "In summary, our results indicate that the tumor-promoting role of prostatic TAMs may be partially ascribed to up-regulation of let-7b, which regulates expression of IL-12, IL-23, IL-10 and TNF-α." (PMID 27157642, 2016). "The IL-10−/− mice had significantly fewer tumor foci in the lungs compared with the WT mice." (PMID 27075020, 2016). "In addition, expression of factors that initiate the resolution of inflammation (IL-10, Tgf-β) were also diminished one day after wounding in wound tissues of tumor-bearing mice relative to controls." (PMID 27548621, 2016). "We next examined the tumor cells for secretion of IL-10, the signature CD1dhiCD5+ Breg cytokine." (PMID 27959896, 2016). "IL-10 is often used by tumour cells to suppress the immune response in order to escape detection." (PMID 27412241, 2016). "However, TGF-β or IFN-γ-producing TDLN Treg cells were reduced in IL-10−/− or WT tumor-bearing mice after anti-TGF-β treatment." (PMID 27075020, 2016). "Therefore, reduced synthesis and secretion of IL-6, MCP-1, and IL-10 were, at least in part, responsible for the decreased stimulation of tumor growth and metastasis by lal−/− MSCs, which formulate a unique signature for lal−/− MSCs." (PMID 27531897, 2016). "Interestingly, in contrast to several autoimmune models the adoptive transfer of either WT or IL-10−/− B cells was capable of rescuing tumor growth in the EMT-6 model." (PMID 27437104, 2016). "Lin and Karin reported that IL-10 could modulate apoptosis and suppress angiogenesis during tumor regression, downregulating VEGF, TNF-α, and IL-6 production by TAMs." (PMID 26989335, 2016).
tumor (continued). "In contrast, IL10 expression in the tumor compartment was downregulated (0.39X, [0.02-40.3])." (PMID 27463005, 2016). "Similarly, using IL-10-expressing mouse mammary adenocarcinoma model, it was demonstrated that neutrophils play the key role in the early rejection of the tumour." (PMID 27212807, 2016). "Therefore, we treated IL-10−/− or WT tumor-bearing mice intravenously with an anti-TGF-β Ab (described in the Methods section)." (PMID 27075020, 2016). "In addition, the anti-inflammatory cytokine IL-10 was also increased sharply in two of three clinical samples with neoplasms." (PMID 27252695, 2016). "In this study, we have found that YPF can downregulate TGF-β, IDO, and IL-10 in tumor tissues, which may provide the partial explanation for the YPF-modulated improvement of NK cell function." (PMID 27034590, 2016). "Because EGFR activation may trigger the initial step of IL10 synthesis, its secretion out of cancer cells to develop the tumor microenvironment would benefit cancer development." (PMID 26956044, 2016). "Expression of LAG-3 and PD-1 was up-regulated by IL-10, IL-6 and tumor-derived APCs." (PMID 26700461, 2016). "Finally, TGF-β, which has a role in priming differentiation of IL-10 producing Tr1 cells, was also down-regulated as well in tumour lysate-loaded DCs." (PMID 26795765, 2016). "On the one hand, the immunosuppressive property of IL-10 may suppress anti-tumor immune responses and promote tumor development." (PMID 27995011, 2016). "Second, we studied different Treg populations in IL-10-deficient mice and the influence of the absence of IL-10 on decreased tumor volumes and foci." (PMID 27075020, 2016). "Furthermore, TREM-2+DCs from tumor-bearing mice and CM produced less IL-12 but more IL-10, In addition, we also collected DCs from CM on day 5 and tested its OVA uptake to investigate their endocytosis phenomenon." (PMID 27102437, 2016). "Interleukin-10 (IL-10) is a powerful modulator of anti-tumor immune responses." (PMID 27995011, 2016). "On the other hand, the anti-angiogenic property of IL-10 may inhibit microvasculature formation and tumor growth." (PMID 27995011, 2016). "Interleukin (IL)-10-producing B cells (B10 cells) plays an important role in the tumor tolerance." (PMID 27605397, 2016). "Additionally, the PGE2 effects during the priming of DCs with tumor antigens inhibit completely the DCs ability to produce IL-12 and prompt the production of high levels of IL-10." (PMID 28053982, 2016). "Constitutive STAT3 phosphorylation in tumor cells is usually driven by the overproduction of key cytokines and growth factors, such as IL-6, IL-10, EGF, HGF, Her2/Neu, and VEGF, or their receptors, as well as aberrantly activated cytoplasmic kinases, such as Src, among others." (PMID 27148255, 2016). "The corresponding tumor sizes of the IL10−/− or WT mice are shown." (PMID 27075020, 2016). "Together, these results suggest that TNFα secretion by B cells may regulate tumor growth through production of IL-10+ Bregs, which in turn attenuate CD8+IFN-γ+ T cell responses." (PMID 27437104, 2016). "Conversely, anti-TGF-β significantly decreased tumor VEGF in the IL-10−/− B16/F10 mice." (PMID 27075020, 2016). "We previously reported that purified TDLN B effector cells could kill tumor cells directly involving the Fas/FasL pathway and are regulated by IL-10." (PMID 27528023, 2016). "In comparison to tumor lysate alone, tumor antigen loaded NP pulsed DCs substantially released more IL-12 and IL-10 cytokines, moreover, our findings also revealed that the level of secreted IL-12 was higher than of IL-10 significantly (P ≤ 0.05)." (PMID 27782834, 2016). "Overexpression of the STAT3 protein by tumor cells affects the expression ofseveral immunosuppressive cytokines, including IL-10 and TGF-β, suppressesthe Th1 response, reduces the expression of co-stimulatory molecules and MHCclass II molecules, and activates TGF-β expression in DCs." (PMID 27795841, 2016).
tumor (continued). "However, because the large amounts of IL-10 that are present in the tumor microenvironment play a major role in suppressing the anti-tumor immune response, strategies to break tolerance by neutralizing the function of IL-10 are important for tumor treatment." (PMID 27172902, 2016). "In fact, our data support a notion whereby the infiltrating macrophages within the tumor might have acquired a phenotype characterized by a high production of IL-10, which suppresses the anti-tumor actions of IFN-γ and encourages tumor growth." (PMID 27388564, 2016). "In the tumor microenvironment, the source of IL10 is variable and may include M2 macrophages, lymphocytes, and cancer cells." (PMID 26956044, 2016). "In addition, blocking IL-10 signalling at the time of immunization is able to control tumour growth in mouse model." (PMID 27100390, 2016). "The role of TGF-β was demonstrated by antibody blocking experiments in which anti-IL-10 plus anti-TGF-β antibodies could reproduce the effects of STAT3 targeting of H22 cells in in vivo tumor growth experiments." (PMID 27148255, 2016). "Furthermore, the tumor micro-environment is usually rich in IL-10, which is the major regulator of TRAIL-Rs among the factors tested in this study." (PMID 27191500, 2016). "This pathway is critical for gut homeostasis since IL-10-deficient mice or a deficiency in downstream signaling proteins (STAT3 and SOCS3) results in spontaneous intestinal inflammation as well as increased tumor incidence (in the AOM/DSS model)." (PMID 26998523, 2016). "The immunosuppressive effects of IL-10 in the tumour environment have been repeatedly confirmed." (PMID 27547238, 2016). "In fact, BRAF inhibitors treatment is associated with decreased production of the immunosuppressive factor IL10 and enhanced expression of tumor-specific antigens and so BRAF inhibitors might induce T-cell infiltration before treatment with immunotherapy." (PMID 26863566, 2016). "The activation of these cells (macrophages and B cells) may indicate that both the innate and adaptive immune response are responsive to the presence of Reovirus although interestingly IL-10 was also increased in B16F10 tumours." (PMID 27412241, 2016). "The M1 population is thought to be beneficial in a tumor environment (including solid tumors and circulating tumor cells) but this environment is overwhelmed by anti-inflammatory signals, and type-II cytokines (e.g. IL-4, IL-10 and IL-13) tend to dominate." (PMID 27564103, 2016). "The T cell-suppressive factors Arg1, ROS and IL-10 can also be produced by tumor-promoting TANs." (PMID 27598210, 2016). "IL-10 was required in regulatory T cells (Treg) to reduce tumor burden in ApcMin/+ mice." (PMID 27148488, 2016). "Interestingly, the tumor infiltration of M2 macrophages coincide with an increased tumor expression of the IL-10 in tumors from animals treated with either of the two lipid mediators." (PMID 27388564, 2016). "IL-10 favors tumor malignancy by promoting T cell apoptosis and tumor cell survival." (PMID 27375834, 2016). "It is known that regulatory T cell-mediated/IL-10-dependent suppression of CD8+ T cells can be blocked by removal of tumour-derived HMGB150, which is consistent with our observation that HMGB1 inhibition leads to delayed tumour growth although via an alternate mechanism." (PMID 27426915, 2016). "Targeting IL-10 could be of additional interest in the context of tumor immune evasion, since it is known as an immunosuppressive cytokine." (PMID 27732933, 2016). "Furthermore, we found that YPF significantly downregulated the expression of TGF-β, indoleamine 2,3-dioxygenase, and IL-10 in tumor microenvironment." (PMID 27034590, 2016). "Its presence may indicate that the tumour is making an effort to down regulate the immune response triggered by the virus either by producing IL-10 directly or inducing infiltrating immune cells to do so." (PMID 27412241, 2016).
tumor (continued). "Tumor-induced DCs could inhibit the proliferation of T cells directly through immunosuppressive cytokines such as IL-10 or TGF-β." (PMID 27102437, 2016). "It has been shown that MSCs can polarise macrophages towards this “anti-inflammatory” M2 phenotype, characterised by IL-10 production and decreased iNOS and IL-12 expression, and this likely represents another important mechanism by which MSCs aid tumours in evading immune clearance." (PMID 27542276, 2016). "In addition, the tumor cells, themselves, contribute to immune suppression through the secretion of IL-10 and TGFβ and chemokines that recruit Tregs to the tumor site." (PMID 27153100, 2016). "Additionally, we observed that tumor cells secreted little IL-10, but tumor- containing medium induced a strong IL-10 production by DCs." (PMID 27102437, 2016). "In addition to the effect of IL10 on the tumor microenvironment through the inhibition of immune activity, IL10 also directly promotes the survival of cancer cells." (PMID 26956044, 2016). "IL-10 deficiency in tumor-bearing mice has no inhibitory effect on TGF-β1-derived Tregs obtained from TDLN and tumors, and these effects appear to be opposite in the spleen, where there is an overall increase in TGF-β1-producing Tregs." (PMID 27075020, 2016). "Therefore, we predicted that CSF IL-10 is more likely to be secreted by tumor cells in PCNSL than from the tumor microenvironment." (PMID 27924864, 2016). "In addition, laricitrin treatment also increased tumor-destructive Th1 response by upregulation of the IL-12/IL-10 ratio in DCs in the tumor microenvironment." (PMID 27833081, 2016). "Because the relationship between the immune system and tumor formation is complicated, the action of IL10 as an immune suppressor may have different effects at different stages of cancer progression." (PMID 26956044, 2016). "Moreover, analysis of the IL-12/IL-10 expression profile of the pleural macrophages demonstrated a significant shift towards an M1 anti-tumor phenotype in cysmethynil treated animals." (PMID 26959120, 2016). "Inasmuch as activated FcγRIIlow/− B cells in HCC tumours potently correlated with disease progression and even produced protumorigenic IL-10, we investigated whether FcγRIIlow/− B cells affected CD8+ cytotoxic T-cell immunity in tumours." (PMID 27853178, 2016). "This suggests a tumor-promoting role of IL-10 in CRC patients." (PMID 27148488, 2016). "As a result, infiltrated Tregs can exert suppressive effects on effector CD8+ and CD4+ T cells either through direct cell-to-cell contact or indirectly by generating interleukin-10 (IL-10) and transforming growth factor β (TGFβ) in situ, which helps tumor cells to evade the immune system." (PMID 27389040, 2016). "We observed that conditioned media from M2-polarized, iron-release MΦ (IL-10-treatment) significantly enhanced MCF-7 cancer cell migration, whereas the treatment of tumor cells with supernatants of MΦ previously co-treated with IL-10 and chelator reversed this effect." (PMID 27806101, 2016). "IL-10 has also been shown to promote tumor growth via various pathways." (PMID 27322426, 2016). "Because communication between the tumor microenvironment and tumor cells is critical for cancer development, an experimental model capable of mimicking the tumor environment had to be established to elucidate the role of IL10 in cancer progression." (PMID 26956044, 2016). "IL-10 has been shown to modulate apoptosis and suppress angiogenesis during tumor regression." (PMID 27246354, 2016). "Inflammation plays roles in all phases of tumor development, and IL-10, a well-known immuno-modulatory cytokine, may provide a functional link between inflammation and cancer." (PMID 27811370, 2016). "Similarly, tumor-associated IFN-γ-expressing CD4+ (Th1) cells were significantly increased in WT and IL10−/− B16/F10 mice after anti-TGF-β injection." (PMID 27075020, 2016).